NCKAP1 (NCK associated protein 1)
Diseases named in the same sentence as NCKAP1 in open-access papers (continued):
Sharing a sentence is not in itself a finding about the gene and the disease.
renal carcinoma (2 papers, 2024 to 2025). A carcinoma arising from the epithelium of the renal parenchyma or the renal pelvis. "Our pancancer analyses revealed a complex NCKAP1 expression profile across various cancer types, with reduced levels in renal cancer patients linked to patient prognosis." (PMID 40141455, 2025). "NCKAP1 is also deregulated in renal cancer and is associated with patient outcomes." (PMID 40141455, 2025). "The differential expression of NCKAP1 across these cell types underscores the potential for NCKAP1 to be involved in diverse biological processes and could have implications for understanding the molecular mechanisms underlying renal cancer." (PMID 40141455, 2025). "Collectively, these findings suggest that alterations in NCKAP1 expression significantly influence the aggressive characteristics of renal cancer cells." (PMID 40141455, 2025). "IHC assessment of kidney tissues from the Human Protein Atlas corroborated these findings, demonstrating that NCKAP1 protein expression was lower in renal cancer tissues than in normal kidney tissues." (PMID 40141455, 2025). "Taken together, our results indicate that NCKAP1 is crucial for the biological processes of renal cancer cells and potentially acts as an essential regulator of cell growth, movement, and tissue penetration." (PMID 40141455, 2025). "To further elucidate the role of NCKAP1 in renal cancer, we conducted a series of functional assays to validate its functional contributions." (PMID 40141455, 2025). "Compared with NCKAP1-overexpressing cells, NCKAP1-knockdown cells presented increased proliferation rates, indicating the inhibitory role of NCKAP1 in the proliferation of renal cancer cells." (PMID 40141455, 2025). "We verified that NCKAP1 suppressed the proliferation and invasion of renal cancer cells via the PI3K/AKT/mTOR signaling pathway." (PMID 40141455, 2025). "To further investigate the role of NCKAP1 in renal cancer, we employed Kaplan–Meier (KM) survival curves to assess OS and disease-free survival (DFS) and specifically examined its influence on KIRC." (PMID 40141455, 2025). "Our results indicate that NCKAP1 is a potential predictive marker and treatment target for renal cancer." (PMID 40141455, 2025). "This comprehensive single-gene study has substantially advanced our understanding of the molecular functions of NCKAP1 and provided crucial insights into the mechanisms of renal cancer development." (PMID 40141455, 2025). "The distribution of NCKAP1 in the UMAP plot of the renal cancer single-cell sequencing data was subsequently examined." (PMID 40141455, 2025). "CIBERSORT and single-cell RNA sequencing revealed the expression patterns of NCKAP1 in different cell lineages in renal cancer and a significant correlation between NCKAP1 and immune cell infiltration in the kidney tumor microenvironment." (PMID 40141455, 2025). "Transwell migration and Matrigel invasion assays revealed that cells with downregulated NCKAP1 expression presented increased migratory and invasive capabilities, suggesting that NCKAP1 suppresses the metastatic potential of renal cancer cells." (PMID 40141455, 2025). "To evaluate the clinical significance of NCKAP1, we analyzed the relationships between NCKAP1 expression and clinical features in 897 patients with renal cancer, including KIRC (n = 541), KIRP (n = 291) and KICH (n = 65) from the TCGA datasets." (PMID 40141455, 2025). "We further verified that NCKAP1 suppressed cancer cell growth and affected tumor development in renal cancer via the PI3K/AKT/mTOR signaling pathway." (PMID 40141455, 2025). "In this study, we demonstrated that NCKAP1 inhibited the growth and progression of renal cancer cells via the PI3K/AKT/mTOR signaling pathway, providing a molecular basis for its potential as a therapeutic target." (PMID 40141455, 2025). "Moreover, immunoblotting was also used to investigate the regulatory effect of NCKAP1 on the PI3K/AKT/mTOR signaling pathway in renal cancer cells." (PMID 40141455, 2025).
renal carcinoma (continued). "Furthermore, we applied comprehensive scRNA-seq to investigate the function of NCKAP1 in the renal cancer microenvironment via data from the TCGA database." (PMID 40141455, 2025). "In this study, we investigated whether NCKAP1 was expressed at lower levels in renal cancer, which was correlated with more favorable clinical outcomes." (PMID 40141455, 2025). "Further investigations into the functional significance of NCKAP1 in these cell types may provide valuable insights into its role in renal cancer." (PMID 40141455, 2025). "Moreover, mRNA analysis of renal carcinoma cells revealed that the expression level of NCKAP1 in multiple renal cancer cell lines was significantly lower than that in the normal cell line HK-2." (PMID 40141455, 2025). "Additionally, we analyzed the downstream pathways regulated by NCKAP1 in renal cancer." (PMID 40141455, 2025). "However, the functions of NCKAP1 in the progression of renal cancer are yet unknown." (PMID 40141455, 2025).
Sepsis (2 papers, 2024 to 2025). Sepsis is defined as life-threatening organ dysfunction caused by a dysregulated host response to infection. "Notably, the expression patterns of core PCD-related genes in this cohort were highly consistent with those observed in the discovery datasets, with genes such as CYBB, GCLM, MAP1LC3B, NCKAP1, and PGD markedly upregulated in sepsis patients." (PMID 41346577, 2025).
absence seizures (1 paper, 2025). "Four genes-HESX1, NCKAP1, SON, STARD9-had not been previously associated with absence seizures." (PMID 41137852, 2025).
acute aortic dissection (1 paper, 2024). "Similarly, miR-140-5p suppression has been observed in acute aortic dissection (AAD) patients, correlating with upregulated NCKAP1 levels, influencing VSMC proliferation, migration, and invasion." (PMID 38511055, 2024).
amyotrophic lateral sclerosis (1 paper, 2021). Amyotrophic lateral sclerosis (ALS) is a neurodegenerative disease characterized by progressive muscular paralysis reflecting degeneration of motor neurons in the primary motor cortex, corticospinal tracts, brainstem and spinal cord. "In addition, in the microglia of amyotrophic lateral sclerosis (ALS) patients, the decreased expression of NCKAP1 was also significantly correlated with defective phagocytic function and abnormal actin polymerization." (PMID 34440217, 2021).
bladder urothelial carcinoma (1 paper, 2025). "Differential NCKAP1 was also revealed via the GEPIA platform across different cancer stages, especially for bladder urothelial carcinoma (BLCA), KIRC, and several other specific cancer types, with noteworthy outcomes." (PMID 40141455, 2025).
colon adenocarcinoma (1 paper, 2023). "In the blood cells of PDX mice, a significant increase in NCKAP1 was confirmed by quantitative PCR analysis in four cases of colon adenocarcinoma." (PMID 36639705, 2023).
colon cancer (1 paper, 2023). "We found that NCK-associated protein 1 (NCKAP1) was significantly increased in the blood RNA of patient-derived xenograft (PDX) models of colon cancer." (PMID 36639705, 2023). "Interestingly, while the wound gap was more rapidly closed in TGFβ1-treated colon cancer cells, the gap area closure caused by treatment with TGFβ1 was inhibited by NCKAP1 knockdown." (PMID 36639705, 2023). "Tumors were successfully grown in all groups of HCT116 colon cancer cells; however, the growth rate of shScramble-treated cells was more rapid than that of NCKAP1 knockdown cells." (PMID 36639705, 2023). "Two kinds of liver metastasis mouse models using NCKAP1 knockdown stable colon cancer cell lines showed dramatic inhibition of tumor growth and metastasis." (PMID 36639705, 2023). "In the NCKAP1 gene knockdown-induced human colon cancer cell lines HCT116 and HT29, there was a reduced wound healing area and significant inhibition of migration and invasion." (PMID 36639705, 2023). "When NCKAP1 expression was decreased by siRNA transfection in colon cancer cells, the levels of CDH1 and CTNNB1, which are known as epithelial marker among EMT markers, were increased." (PMID 36639705, 2023). "To identify the function of NCKAP1 in metastasis in colon cancer, we conducted in vitro assays to test EMT ability." (PMID 36639705, 2023). "We established metastasis models for colon cancer to liver transition by intrasplenic injection shRNA of NCKAP1-transfected HCT116 cells or by implanting tumor tissue generated with the cells on cecal pouch." (PMID 36639705, 2023). "this study emphasizes that colon cancer diagnosis using the expression level of NCKAP1 and the development of NCKAP1 gene expression inhibitors can be useful treatment strategies in the clinic." (PMID 36639705, 2023). "NCKAP1 was also expressed in tumor mass as well as in the blood cells of colon cancer PDX mice." (PMID 36639705, 2023). "Furthermore, the increase in FN induced by TGFβ1 was decreased in NCKAP1 knockdown colon cancer cells." (PMID 36639705, 2023). "NCKAP1 was successfully knocked down by siRNA transfection in HCT116 and HT29 colon cancer cells, and its expression was confirmed by quantitative PCR and western blot." (PMID 36639705, 2023). "TGFβ1-treated colon cancer cells underwent morphological changes, including adopting a mesenchymal shape, but NCKAP1 knockdown cells did not change to a mesenchymal morphology after treatment with TGFβ1." (PMID 36639705, 2023). "Epithelial character was weakened in TGFβ1-treated colon cancer cells, but their epithelial properties did not disappear in the NCKAP1 knockdown state even when they were treated with TGFβ1." (PMID 36639705, 2023).
congenital heart disease (1 paper, 2025). A heart disease that is present at birth. "To date, this represents the fourth reported case of a likely disruptive NCKAP1 variant in a patient presenting with congenital heart defect and/or neurodevelopmental delay." (PMID 41462819, 2025). "Here, we present a case of a patient with neurodevelopmental delay and congenital heart disease (CHD) harboring a novel damaging NCKAP1 variant." (PMID 41462819, 2025). "Here, we report a patient with a de novo heterozygous loss-of-function variant in NCKAP1 who presented with both neurodevelopmental delay and a complex congenital heart disease (CHD), specifically, infradiaphragmatic total anomalous pulmonary venous return (TAPVR)." (PMID 41462819, 2025).
developmental delay (1 paper, 2025). "We report a patient with a heterozygous de novo loss-of-function frameshift variant in NCKAP1, NM_205842.3:c.2956_2959del p.(Ser986Hisfs*34), who presented with CHD (infradiaphragmatic TAPVR) and developmental delay." (PMID 41462819, 2025).
endometrial cancer (1 paper, 2025). Primary or metastatic malignant neoplasm involving the endometrium (mucous membrane that lines the endometrial cavity). "Moreover, NCKAP1 genetic variations were investigated via cBioPortal, which indicates that endometrial cancer (EC) has the highest incidence of alterations, with approximately 6% of the cases affected." (PMID 40141455, 2025).
gastric tumors (1 paper, 2025). "It is suggested that the regulation of NCKAP1 by miR383-5p may be involved in the metastasis of gastric tumors." (PMID 38625593, 2025).
kidney cancer (1 paper, 2025). Primary or metastatic malignant neoplasm involving the kidney. "To explore the underlying mechanisms of the effect of NCKAP1 on kidney cancer, we conducted RNA sequencing analysis of 769P cells with increased NCKAP1 expression." (PMID 40141455, 2025). "RNA sequencing of NCKAP1-overexpressing 769P cells further examined the impact of NCKAP1 on kidney cancer." (PMID 40141455, 2025). "Our findings underscore the significant impact of NCKAP1 on the clinical outcomes of kidney cancer patients, highlighting its potential as a prognostic biomarker and a promising target for therapeutic interventions." (PMID 40141455, 2025). "The increased expression of NCKAP1 in kidney cancer indicates its potential as a prognostic indicator for suppressing cellular proliferation in clear cell RCC." (PMID 40141455, 2025). "Our findings indicate that NCKAP1 may function as a tumor suppressor in kidney cancer, highlighting its role in impeding tumor progression." (PMID 40141455, 2025). "Moreover, NCKAP1-depleted tumors exhibit fibrotic stroma with increased collagen deposition and enhanced immune infiltration, indicating that NCKAP1 plays a crucial role in the advancement of tumors and preservation of tumor tissue structure in kidney cancer." (PMID 40141455, 2025).
lymphedema (1 paper, 2025). Excess fluid collection in tissues, causing swelling. "Based on the patient’s clinical presentation, absence of alternative etiologies, and lack of other pathogenic genetic variants, we propose localized lymphedema as a potential associated phenotype of NCKAP1 variation." (PMID 40551827, 2025). "Lymphedema associated with NCKAP1 variants has not been previously reported." (PMID 40551827, 2025).
neuroblastoma (1 paper, 2009). Neuroblastoma (NB) is the most common solid, extracranial childhood tumor. "In sporadic AD, human Nck associated protein 1's (Nap1) expression is downregulated, leading to apoptosis in human neuroblastoma cells." (PMID 19602287, 2009).
Neurodevelopmental delay (1 paper, 2025). "This represents the fourth reported case linking NCKAP1 variants to CHD and/or neurodevelopmental delay." (PMID 41462819, 2025).
Obesity (1 paper, 2025). Accumulation of substantial excess body fat. "However, obesity is supported as an association of NCKAP1 variation in past reports, and thus, these conditions are essential to highlight, as screening for obesity-related comorbidities may be considered advisable." (PMID 40551827, 2025). "More comprehensive data could help determine whether obesity and its related health outcomes are consistently part of the NCKAP1-related NDD spectrum or more coincidental in isolated cases." (PMID 40551827, 2025).
ovarian epithelial tumor (1 paper, 2025). A benign, borderline, or malignant tumor that originates from the surface epithelium of the ovary. "The prevalence of NCKAP1 amplification was highest in ovarian epithelial tumors, occurring in approximately 2.5% of cases." (PMID 40141455, 2025).
Parkinson disease (1 paper, 2025). A progressive degenerative disorder of the central nervous system characterized by loss of dopamine producing neurons in the substantia nigra and the presence of Lewy bodies in the substantia nigra and locus coeruleus. "In contrast, the Amyg showed upregulation of genes linked to oxidative phosphorylation (Atp6v1e1, Atp5mc2, Atp6v0e2), Parkinson disease (Snca, Calm1, Slc39a10), and regulation of actin cytoskeleton (Arpc3, Nckap1, Cfl1), indicating increased mitochondrial metabolism and structural plasticity." (PMID 41394722, 2025).
testicular germ cell tumor (1 paper, 2025). A germ cell tumor arising from the testis. "In contrast, high NCKAP1 expression was associated with better prognosis in KIRC (p = 0.004) and testicular germ cell tumors (TGCTs, p = 0.038)." (PMID 40141455, 2025).
tumor (25 papers, 2019 to 2025). "Research has shown that NCKAP1 is highly expressed in tumor cells and its expression levels are linked to the prognosis of diseases such as breast, prostate, and colon cancer." (PMID 38739940, 2024). "As a novel diagnostic marker, the feasibility of NCKAP1 was assessed in patient samples of tumor tissues and bloods." (PMID 36639705, 2023). "The Gene Ontology (GO) and the Kyoto Encyclopedia of Genes and Genomes (KEGG) analyses indicate that NCKAP1 is strongly associated with cell death and tumor immunity." (PMID 37928421, 2023). "Using the UALCAN database, we examined the correlation between NCKAP1 expression and various clinicopathological features of ccRCC and found that NCKAP1 mRNA expression was significantly associated with tumor grade, TNM stage, and lymph node metastasis." (PMID 35957696, 2022). "Our results showed that NCKAP1 expression in tumor cells in HCC tissue specimens was negatively associated with malignant clinicopathological features, therefore, we explored the potential biological function of NCKAP1 in HCC tumorigenesis." (PMID 31068575, 2019). "NCKAP1 encodes a protein that is involved in cellular adhesion, cytoskeletal organization, and signal transduction and is associated with the pathogenesis of various neoplasms." (PMID 40141455, 2025). "Studies show that NCKAP1 drives the actin assembly and polymerization as well as the formation of lamellipodia, which is essential for cell motility and adhesion, and this is associated with the development of tumor invasive and metastatic phenotypes." (PMID 38625593, 2025). "Furthermore, multivariate analyses revealed that NCKAP1 expression in tumor cells was an independent risk factor affecting recurrence and survival following curative surgery." (PMID 31068575, 2019). "First, NCKAP1 expression levels were compared between paracancerous and tumor tissues, revealing a significant reduction in NCKAP1 expression in tumor tissues, suggesting a potential role for NCKAP1 in tumorigenesis." (PMID 40141455, 2025). "Our findings underscore the intricate relationship between NCKAP1 expression and immune cell dynamics in the TME, suggesting that NCKAP1 plays a role in modulating tumor behavior and immune responses in cancer." (PMID 40141455, 2025). "The expression of NCKAP1 mRNA was significantly correlated with several factors, including advanced pathological T and M grades, tumor grade, disease stage, and sex." (PMID 40141455, 2025). "In Tumor 2, HPV16 was integrated into the first intron of the Nck-associated protein 1 gene (NCKAP1) gene on chromosome 2, with the viral genome oriented in the opposite transcriptional direction as NCKAP1." (PMID 38898085, 2024). "In human kidney cancer cells (ACHN), the overexpression of NCKAP1 decreases the cells' invasive and migratory capabilities of the tumor cells, thereby suppressing cancer progression." (PMID 38739940, 2024). "Our experimental results confirmed this point of view and revealed that NCKAP1 also affects tumor cell migration, proliferation and clone formation in LUAD." (PMID 38223725, 2024). "The potential role of NCKAP1 in promoting disulfidptosis in tumor cells requires further investigation." (PMID 38685115, 2024). "The expression of SLC7A11, SLC3A2, RPN1 and NCKAP1 were found to be upregulated in the tumor tissues compared with that in the corresponding normal tissues from the TCGA data." (PMID 38528532, 2024). "Among tumor types, UCEC was found to present the most widespread somatic mutations of the disulfidptosis genes, such as SLC7A11 (92 %), NCKAP1 (85 %), LRPPRC (75 %), and OXSM (75 %)." (PMID 39605832, 2024). "These in vivo data demonstrated that NCKAP1 regulates metastasis into distant organs and tumor growth in the mimic microenvironment." (PMID 36639705, 2023).